ERGIC1 (endoplasmic reticulum-golgi intermediate compartment 1)
Description:
Possible role in transport between endoplasmic reticulum and Golgi.
Synonyms: ERGIC-32; ERGIC32; KIAA1181; NET24; AMC2; AMCN
Tractability: Antibody: UniProt predicts a signal peptide or a membrane-spanning region. PROTAC: ubiquitination databases record sites on it; its protein half-life has been measured.
Gene: Protein-coding gene on chromosome 5 (172,834,251 to 172,952,792, forward strand). Ensembl gene ENSG00000113719.
Subcellular location: Endoplasmic reticulum membrane; Endoplasmic reticulum-Golgi intermediate compartment membrane; Golgi apparatus membrane
Subcellular location (Human Protein Atlas): Nucleoplasm; Vesicles
Gene Ontology:
Molecular function: protein binding
Biological process: endoplasmic reticulum to Golgi vesicle-mediated transport; retrograde vesicle-mediated transport, Golgi to endoplasmic reticulum
Cellular component: endoplasmic reticulum membrane; endoplasmic reticulum-Golgi intermediate compartment; endoplasmic reticulum-Golgi intermediate compartment membrane; Golgi membrane; membrane; nucleoplasm; COPII-coated ER to Golgi transport vesicle; endoplasmic reticulum
Genetic constraint (gnomAD): Loss-of-function variants: 18 observed, 39.05 expected, observed/expected ratio (o/e) 0.46, 90% interval 0.32 to 0.68. The synonymous counts are far from expectation, so gnomAD's model fits this gene poorly and the ratio says little. Missense variants: 284 observed, 400.68 expected, observed/expected ratio (o/e) 0.71, 90% interval 0.64 to 0.78. Synonymous variants: 123 observed, 163.37 expected, observed/expected ratio (o/e) 0.75, 90% interval 0.65 to 0.88.
Homologues: Orthologues: chimpanzee ERGIC1 (100% identical), guinea pig ERGIC1 (99% identical), mouse Ergic1 (99% identical), dog ERGIC1 (98% identical), rat Ergic1 (97% identical), macaque ERGIC1 (90% identical), zebrafish ergic1 (90% identical), tropical clawed frog ergic1 (86% identical), pig ERGIC1 (83% identical), rabbit ERGIC1 (80% identical), Caenorhabditis elegans ergi-1 (56% identical). Paralogues in human: ERGIC3 (34% identical), ERGIC2 (27% identical).
Diseases named in the same sentence as ERGIC1 in open-access papers:
ERGIC1 is named in the same sentence as 13 diseases in open-access papers, as found by Europe PMC text mining. Sharing a sentence is not in itself a finding about the gene and the disease. The quoted sentences say what the papers report.
prostate carcinoma (2 papers, 2012 to 2021). A carcinoma that arises from epithelial cells of the prostate gland. "ERGIC1 silencing specifically regulated the proliferation of ERG oncogene positive prostate cancer cells and inhibited ERG mRNA expression in these cells, indicating that it is a potent drug target in ERG positive subgroup of prostate cancers." (PMID 22761906, 2012). "Interestingly, high expression levels of ERGIC1 are revealed in prostate cancer tissues, and its silencing down-regulates the ERG oncogene." (PMID 34439361, 2021). "Surprisingly, although ERG1C1 expression was associated with AR and AR driven ERG expression in clinical prostate cancers, no major changes were observed in the expression of ERGIC1 mRNA expression in response to AR silencing." (PMID 22761906, 2012). "Moreover, this study associates ERGIC1 and TMED3 expression with ERG oncogene expression, supporting their potential in the management of prostate cancer." (PMID 22761906, 2012). "Due to the function of AR as an important oncogene in prostate cancer, the effect of AIM1, ERGIC1, TMED3, and TPX2 expression on AR signaling was analyzed." (PMID 22761906, 2012). "The mRNA expression of AIM1, ERGIC1, TMED3, and TPX2 was studied in six prostate cancer (VCaP, PC-3, MDA-PCa-2b, LNCaP, DU145 and 22Rv1) and three non-malignant prostate epithelial cell lines (RWPE-1, PrEc, EP156T)." (PMID 22761906, 2012). "Taken together, these results suggest that the expression of the potential novel drug targets AIM1, ERGIC1, TMED3, and TPX2 is promoted by ERG oncogene and androgens in cultured prostate cancer cells." (PMID 22761906, 2012). "Functional gene ontology annotations for the genes co-expressed (R >0.5 and P<0.001) with AIM1, ERGIC1, TMED3 or TPX2 in clinical prostate cancer samples (n = 66–329)." (PMID 22761906, 2012). "AIM1, ERGIC1, and TPX2 were shown to be highly expressed especially in prostate cancer tissues, and high mRNA expression of ERGIC1 and TMED3 associated with AR and ERG oncogene expression." (PMID 22761906, 2012). "In order to illustrate the potential of the selected putative targets in the treatment of hormone-refractory disease, the efficacy of AIM1, ERGIC1, TMED3, and TPX2 silencing in the inhibition of prostate cancer cells cultured in androgen deprived conditions was studied." (PMID 22761906, 2012). "Moreover, AIM1, ERGIC1, and TPX2 were shown to be highly expressed specifically in prostate cancer tissues, thereby confirming the results of the bioinformatic surveys." (PMID 22761906, 2012). "Validation of target gene expression patterns in clinical prostate samples confirmed that AIM1, ERGIC1, and TPX2 mRNA levels were significantly elevated in prostate cancer tissues (n = 33), compared to non-malignant control tissue samples (n = 3)." (PMID 22761906, 2012). "In addition, although ERGIC1 and TMED3 were highly expressed in both ERG negative and positive prostate cancers, their mRNA expression levels positively correlated with ERG expression levels in ERG positive samples (P = 0.002 and P = 0.007 respectively)." (PMID 22761906, 2012).
arthrogryposis (1 paper, 2025). A rare, non-progressive congenital disorder characterized by multiple joint contractures which are present at birth. "Also, ERGIC1 is a candidate gene associated with arthrogryposis, a systemic disease of the musculoskeletal system characterized by contracture and deformity of the limbs and underdevelopment of joints and muscles." (PMID 40427364, 2025).
glioma (1 paper, 2021). A benign or malignant brain and spinal cord tumor that arises from glial cells (astrocytes, oligodendrocytes, ependymal cells). "The survival analysis in brain lower-grade glioma demonstrates a higher survival probability of individuals with medium/low expression level of ERGIC1, than in individuals with high expression levels." (PMID 34439361, 2021).
pancreatic adenocarcinoma (1 paper, 2021). "Indole-3-carbinol affects the expression of 5 different genes (CD47, CENPB, ERGIC1, PPRC1, SLC44A1) that, in turn, affect the survival in patients with uterine corpus endometrial carcinoma (CD47), brain lower-grade glioma (CENPB, ERGIC1) and pancreatic adenocarcinoma (PPRC1, SLC44A1), respectively." (PMID 34439361, 2021).
prostate tumors (1 paper, 2012). "Since ERGIC1 was highly expressed in most primary prostate tumors, and ERGIC1 silencing was able to downregulate ERG expression, it is an intriguing potential drug target especially for the ERG oncogene expressing tumors." (PMID 22761906, 2012). "Since ERGIC1 and TMED3 expression correlated with ERG expression levels in ERG positive primary prostate tumors, the potential effect of their expression on ERG mRNA expression was studied in VCaP cell line." (PMID 22761906, 2012).
cancer (2 papers, 2012 to 2021). A tumor composed of atypical neoplastic, often pleomorphic cells that invade other tissues. "The gene ERGIC1 is down-regulated under Tamoxifen apoptotic treatment and in Indole-3-Carbinol nutrigenomics treatment, while it is up-regulated in 7 different cancer types." (PMID 34439361, 2021). "Although the exact role of ERGIC1 and TMED3 in cancer remains to be elucidated, the dysfunction of proteostasis and ER is known to induce a stress response (unfolded protein response) leading to apoptosis in cancer cells." (PMID 22761906, 2012). "Furthermore, the gene co-expression signatures indicate that ERGIC1 and TMED3 are expressed together with genes involved in cellular redox homeostasis, in agreement to our earlier results demonstrating that ERG oncogene expressing cancer cells are sensitive to oxidative stress inducers." (PMID 22761906, 2012). "All cancer samples expressed AIM1 mRNA at higher levels than any of the non-malignant samples; while ERGIC1 was over-expressed in 94% (n = 31), and TPX2 in 64% (n = 23) of the cancer samples." (PMID 22761906, 2012). "Especially ERGIC1 and TMED3 were found to be highly expressed in the cancer but not in the non-malignant cell lines." (PMID 22761906, 2012).
tumor (2 papers, 2021 to 2025). "Conversely, SASP factors such as ATL3 and ERGIC1 demonstrated favorable prognostic outcomes, indicating potential tumor-suppressive roles." (PMID 39858632, 2025). "In contrast, factors like ATL3 (Log2 ratio 1.40), ERGIC1 (Log2 ratio 1.64), SPON1 (Log2 ratio 1.25), TNFAIP8 (Log2 ratio 1.99), and VDAC1 (Log2 ratio 1.20), associated with a “highly favorable” prognosis, suggest roles in tumor suppression." (PMID 39858632, 2025). "Moreover, findings suggesting the tumor-suppressive properties of IR-induced SASP including ATL3 and ERGIC1 also align well with earlier studies." (PMID 39858632, 2025).
ERGIC1 also shares sentences with these, for which no sentence is quoted: asthma (2 papers); breast carcinoma (1); COVID-19 (1); infection (1); renal carcinoma (1); uterine corpus endometrial carcinoma (1).